CGAS (cyclic GMP-AMP synthase)
Diseases named in the same sentence as CGAS in open-access papers (continued):
Sharing a sentence is not in itself a finding about the gene and the disease.
type 2 diabetes (5 papers, 2020 to 2024). "Our data revealed a substantial increase in activity in the inflammatory cGAS/STING pathway associated with type 2 diabetes in the kidneys of T2DN rats." (PMID 39589791, 2024). "However, to our knowledge, the activity of the cGAS/STING pathway in aging and sexual dimorphism in DKD associated with type 2 diabetes has not been described previously." (PMID 39589791, 2024). "To investigate whether cGAS-STING is involved in the pathogenesis of diabetic vascular disease, we first searched the available databases and found that STING was significantly upregulated in the leukocytes from type 2 diabetes patients with macrovascular complications (DMCs) in published datasets." (PMID 38129863, 2023). "We revealed that the cyclic GMP-AMP synthase (cGAS)/stimulator of interferon genes (STING) pathway was upregulated in T2DN rats compared with nondiabetic Wistar rats and in type 2 diabetic human kidneys." (PMID 39589791, 2024).
viral hepatitis (5 papers, 2021 to 2025). An acute or chronic inflammation of the liver parenchyma caused by viruses. "In viral hepatitis, activation of the cGAS-STING pathway inhibits viral propagation and virion formation, thereby enhancing the immune response mounted by the host against the virus." (PMID 40098962, 2025). "Specifically, we explore the complex interplay of cGAS-STING signaling in viral hepatitis, ALD, MASLD, and HCC, and discuss its potential as a therapeutic target." (PMID 40098962, 2025). "Secondly, we will delve into how the cGAS-STING pathway is implicated in various liver conditions, including viral hepatitis, MASLD, and ALD, exploring its diverse functions in each." (PMID 40098962, 2025). "Furthermore, modulating cGAS-STING activity may offer therapeutic avenues for viral hepatitis and chronic liver diseases like MASLD and ALD, either by boosting antiviral responses or mitigating inflammation." (PMID 40098962, 2025). "As a critical cytosolic DNA sensor, cGAS-STING has drawn considerable research attention owing to its antiviral capability and role in innate immunity and many studies have focused on viral hepatitis." (PMID 39183465, 2024).
acute myeloid leukemia (4 papers, 2024 to 2025). Acute myeloid leukemia (AML) is a group of neoplasms arising from precursor cells committed to the myeloid cell-line differentiation. "For acute myeloid leukemia, increasing cell turnover rate accelerated the release of mtDNA, which was processed by bone marrow-derived macrophages via LC3-associated phagocytosis and activated cGAS/STING signaling." (PMID 38584255, 2024). "As demonstrated in several acute myeloid leukemia (AML) cell lines treated with a CIN-inducing monopolar spindle 1 (MPS1) kinase inhibitor, micronuclei generation, activation of cGAS/STING signaling, and induction of IFN-β are the consequences of chromosome mis-segregation." (PMID 40098954, 2025).
acute respiratory distress syndrome (4 papers, 2024 to 2025). Progressive and life-threatening pulmonary distress in the absence of an underlying pulmonary condition, usually following major trauma or surgery. "4-octyl itaconate can ameliorate alveolar macrophage pyroptosis in acute respiratory distress syndrome by rescuing mitochondrial dysfunction and inhibiting the cGAS/STING pathway." (PMID 38693472, 2024).
adenomyosis (4 papers, 2021 to 2025). The growth of endometrial tissue inside the muscular wall of the uterine corpus. "And this expression pattern was not related to the type of adenomyosis, with both diffuse and focal adenomyosis showing an increase of cGAS-STING signals." (PMID 39445027, 2024). "The cGAS-STING pathway as a popular molecular pathway in the regulation of the immune system has been shown to be involved in the pathogenesis of adenomyosis." (PMID 39445027, 2024). "This suggests that targeting the cGAS-STING pathway could serve as an effective therapeutic strategy for adenomyosis, providing important experimental evidence for the treatment of adenomyosis by targeting the cGAS-STING signaling pathway." (PMID 41278208, 2025). "The mechanism of cGAS activation in adenomyosis requires further investigation." (PMID 39445027, 2024). "Our study reveals that the cGAS–STING pathway is activated in adenomyosis patients and its activation is subsequently correlated with clinical outcomes, which suggests that the cGAS–STING pathway may contribute to adenomyosis pathogenesis." (PMID 34010983, 2021). "In conclusion, our study reveals that the cGAS–STING pathway is activated in adenomyosis patients and its activation is subsequently correlated with clinical outcomes, which suggests that the cGAS–STING pathway may contribute to adenomyosis pathogenesis." (PMID 34010983, 2021). "We hypothesized that the cGAS–STING pathway might be activated in local tissue in adenomyosis patients and played an important role in adenomyotic development." (PMID 34010983, 2021). "Both diffuse and focal adenomyosis showed increase of cGAS–STING signals." (PMID 34010983, 2021). "Therefore, targeting the cGAS-STING signaling pathway may be a potential therapeutic direction for addressing the chronic inflammatory response in adenomyosis." (PMID 41278208, 2025). "Thus, the inhibition of the key target gene of the cGAS-STING pathway may contribute to the treatment of adenomyosis." (PMID 39445027, 2024). "Multiple studies have confirmed that the pathogenesis of adenomyosis is related to several signaling pathways, such as VEGF,Wnt, PI3K, MAPK, NF-κB, cGAS-STING, TGF-β, Hedgehog, and Hippo pathways." (PMID 41278208, 2025). "In addition, due to the chronic inflammatory mechanism of adenomyosis and the fact that targeting this signaling pathway can affect the anti-infection ability, it is particularly important to understand the minimum inhibition level for the treatment targeting the cGAS-STING signaling pathway." (PMID 41278208, 2025). "The cGAS-STING pathway is an essential signaling mechanism in innate immunity, and it plays an important role in chronic inflammation and abnormal cell proliferation of adenomyosis." (PMID 41278208, 2025). "The cGAS‐STING pathway may be activated in the tissues of patients with adenomyosis, while patients with adenomyosis usually suffer subfertility." (PMID 39113346, 2024). "In this study, we aimed to investigate whether the cGAS–STING pathway was activated and correlated with clinical outcomes in adenomyosis patients." (PMID 34010983, 2021). "Therefore, targeting inflammation-related signaling pathways, such as NF-κB and cGAS-STING, may alleviate the symptoms of adenomyosis." (PMID 41278208, 2025). "The cGAS, STING, TANK‐binding kinase 1 (TBK‐1), interferon‐α (IFN‐α), IFN‐β, and tumor necrosis factor‐α (TNF‐α) mRNA and protein levels in the ectopic endometrial tissue from adenomyosis patients were significantly higher compared with that from the controls in endometrium (p < .05)." (PMID 34010983, 2021). "Our results showed that cGAS and STING were highly elevated in the adenomyosis patients but not in the control patients." (PMID 34010983, 2021).
anemia (4 papers, 2019 to 2024). A reduction in the number of red blood cells, the amount of hemoglobin, and/or the volume of packed red blood cells. "In the deoxyribonuclease II (DNase II)-deficient autoimmune model, apoptotic bodies accumulated in macrophages, which activated the cGAS pathway to produce IFNs and cause lethal anemia (44, –46)." (PMID 39254994, 2024). "In a Tet2-deficient mouse HSPC transplant model, we found cGAS inhibition restored hemoglobin production, resolved anemia, and suppressed monocyte production." (PMID 35788117, 2022). "Finally, the impaired progenitor cell compartments and embryonic anemia seen in PichΔ/Δ mice were rescued by the additional deletion of cGAS." (PMID 35037428, 2022). "Mechanistically, caspase-1 degraded the master erythroid transcription factor, GATA binding protein 1, provoking anemia and myeloid lineage bias that was reversed by cGAS inhibition in vitro and in Tet2–/– hematopoietic stem and progenitor cell–transplanted mice." (PMID 35788117, 2022).
aortic aneurysm (4 papers, 2021 to 2025). A ruptured aneurysm located in the wall of the proximal portion of the descending aorta proceeding from the arch of the aorta. "Additionally, cGAS‐STING activation was linked to phenotypic switching of VSMCs to an inflammatory phenotype in patients with aortic aneurysm and dissection." (PMID 40279334, 2025).
ataxia telangiectasia (4 papers, 2021 to 2024). Ataxia-telangiectasia is the association of severe combined immunodeficiency (affecting mainly the humoral immune response) with progressive cerebellar ataxia. "In the context of ataxia-telangiectasia, a neurodegenerative disorder marked by chronic inflammation, neurodegeneration, and premature aging, cGAS has a direct role in initiating the SASP linked to chronic inflammation." (PMID 37941028, 2023). "In a human brain organoid model of ataxia-telangiectasia, suppressing the cGAS-STING pathway resulted in a reduction of the SASP and its related neuropathology." (PMID 37941028, 2023).
breast tumor (4 papers, 2023 to 2025). "However, the latest research has also shown that cGAS-STING activation facilitated breast tumor progression in mouse xenograft models, and knockdown of cGAS or STING expression prevents tumor metastasis." (PMID 37221584, 2023). "Both in vitro and in vivo studies reveal that by triggering pyroptosis and activating the cGAS‐STING pathway, our nanodrugs exhibit potent cytotoxicity and accurate selectivity in eradicating orthotopic breast tumors." (PMID 39555815, 2025). "By assessing the induction of IFN‐I response, we found that CS‐5BImi, CS‐5BThi, and CS‐6Ind can effectively upregulate the expression of Ifnβ1, a key marker of cGAS‐STING activation, in 4T1 breast tumor cells." (PMID 39999304, 2025). "The results demonstrate that, by triggering pyroptosis and activating the cGAS‐STING pathway, the nanodrugs exhibit potent cytotoxicity and accurate selectivity in eradicating orthotopic breast tumors, and activate an antitumor immune response against lung and bone metastases." (PMID 39555815, 2025).
colorectal adenocarcinoma (4 papers, 2022 to 2026). The most common type of colorectal carcinoma. "Midostaurin inhibited colorectal adenocarcinoma cell growth associated with the formation of dsDNA and ssDNA; the up-regulation of mRNA expression of cGAS, STING, IRF3, and IFNAR1; the down-regulation of Trex-1, c-Kit, and Flt3 protein expression." (PMID 36230769, 2022). "Midostaurin increased mRNA expressions of cGAS, IRF3, and IFNAR1 in colorectal adenocarcinoma cells and mouse spleen macrophages." (PMID 36230769, 2022).
Down syndrome (4 papers, 2021 to 2024). "The micronucleus/cGAS-STING pathway cascade is of particular interest in relation to traits acquired by people with Down syndrome, since several of these traits have been associated with perturbations in inflammatory pathways/immune dysfunction, as well as senescence." (PMID 34283872, 2021). "Our research identifies the cGAS-STING pathway as an upstream regulator responsible for activation of autophagy and inflammatory response in human cells with extra chromosomes, such as in Down syndrome or other aneuploidy-associated pathologies." (PMID 34215848, 2021).
fibrosis (4 papers, 2023 to 2025). the formation of excess fibrous connective tissue in an organ or tissue in a reparative or reactive process. "Furthermore, in mouse models of NASH, the extract reduced histological inflammation and hepatic fibrosis, possibly by inhibiting cGAS-STING pathway activation." (PMID 37081966, 2023).
geographic atrophy (4 papers, 2020 to 2022). "Recently, elevated cGAS level was detected in the RPE of geographic atrophy (GA), an advanced form of dry AMD, and causally linked to RPE degeneration, highlighting the importance of cGAS-STING signaling in dry AMD." (PMID 35347235, 2022). "The amount of cGAS protein is increased in the retinal pigment epithelium (RPE) of the eyes with geographic atrophy, and cGAS is required for Alu-RNA-induced mitochondrial injury and RPE cell death." (PMID 36409895, 2022). "Furthermore, levels of caspase-4, gasdermin D, IFN-β, and cGAS are increased in the RPE of human eyes with geographic atrophy, indicating that cGAS-driven interferon signaling is a route for mitochondrial damage-induced inflammasome activation." (PMID 34718659, 2021).
Hutchinson-Gilford progeria syndrome (4 papers, 2020 to 2025). "Calcitriol, a form of vitamin D, is indicated to suppress the cGAS/STING/IFN signalling in the field of Hutchinson Gilford Progeria Syndrome." (PMID 35644988, 2022). "Expression of a pathological form of Lamin A protein, Progerin, which is at the origin of a very severe premature aging syndrome, Hutchinson-Gilford progeria, also leads to replication defects and an inflammatory phenotype through the cGAS-STING pathway." (PMID 33918867, 2021). "Additionally, aberrant cGAS-STING activation is observed in cells from patients with aging-related diseases like ataxia-telangiectasia, Hutchinson-Gilford progeria syndrome (HGPS), and Werner syndrome." (PMID 40470467, 2025).
myelodysplastic syndrome (4 papers, 2022 to 2024). A clonal hematopoietic disorder characterized by dysplasia and ineffective hematopoiesis in one or more of the hematopoietic cell lines. "Recently, a study showed that the activation of the cGAS/STING/NLRP3 axis by cytoplasmic DNA in Tet2-deficient hematopoietic stem/progenitor cell line promotes myelodysplastic neoplasms development." (PMID 37816954, 2023). "Functionally different mutations have converged to form the cGAS/STING/NLRP3 axis in myelodysplastic syndrome (MDS, a group of cancers in which blood cells are poorly formed and do not work typically) to direct ISG production, pyroptosis, and myeloid lineage skewing." (PMID 38339107, 2024). "NLRP3 inflammasome, pyroptosis and cGAS-STING contribute to neuroinflammation in myelodysplastic syndromes (MDSs) and spinal cord injury (SCI)." (PMID 38195584, 2024). "Moreover, the cGAS-STING pathway was activated in myelodysplastic syndromes (MDS) to induce IFN-stimulated genes (ISG), which triggered the activation of NLRP3 inflammasome." (PMID 38195584, 2024).
oral squamous cell carcinoma (4 papers, 2021 to 2025). "The correlation between cGAS-STING signaling pathway and the tumor immune microenvironment in patients with oral squamous cell carcinoma (OSCC) is unclear." (PMID 34625078, 2021). "Furthermore, keywords such as “mRNA vaccine,” “sonodynamic therapy,” “oral squamous cell carcinoma,” “STING pathway,” and “cGAS-STING pathway” continued to exhibit burstiness until 2024, suggesting that these research directions may continue to gain momentum in the future." (PMID 39247199, 2024).
periodontitis (4 papers, 2021 to 2026). An acute or chronic inflammatory process that affects the tissues that surround and support the teeth. "We then explored the function of the cGAS-STING signaling pathway in a mouse model of periodontitis." (PMID 37405166, 2023). "To explore the role of activation of the cGAS-STING pathway in periodontopathogenic bacteria-induced experimental periodontitis, we examined the effect of P. gingivalis on infection in vitro." (PMID 37405166, 2023). "Second, we believe that it will be more meaningful to use cGAS-and IFNAR1-deficient mice together to study the impact of P. gingivalis on the pathogenesis of periodontitis." (PMID 37405166, 2023). "PubMed/Medline, Scopus, and Web of Science were searched with the terms “STING”, “TBK 1”, “IRF3”, and “cGAS”—alone, or together with “periodontitis”." (PMID 34070809, 2021). "In conclusion, our results demonstrate that the cGAS-STING signaling pathway may be one of the key mechanisms crucial for the P. gingivalis-induced inflammatory response that leads to chronic periodontitis." (PMID 37405166, 2023). "Third, although our work offered insight into cGAS/STING-mediated innate immune responses under periodontitis, the connections between individual pathways remain unknown." (PMID 37405166, 2023). "Furthermore, we used StingGt mice to explore the role of the cGAS-STING pathway in macrophage polarization under periodontitis conditions." (PMID 37405166, 2023). "The literature was searched using the terms “STING”, “STING and periodontitis”, “TBK1”, “TBK 1 and periodontitis”, “IRF3”, “IRF3 and periodontitis”, “cGAS”, and “cGAS and periodontitis” by S.E. and M.Y., using the databases of PubMed/Medline, Scopus, and Web of Science." (PMID 34070809, 2021). "Thus, it cannot be excluded that genetic deletion of Pink1 may exert detrimental effects on periodontitis via M1 polarization through the cGAS-STING pathway." (PMID 38181706, 2024). "However, there is limited knowledge on whether P. gingivalis infection would stimulate inflammatory responses through the cGAS-STING pathway in a periodontitis mouse model, what mechanisms may be involved, and what the functional impact is." (PMID 37405166, 2023). "Thus, to further address the role of the cGAS-STING pathway in vivo, we established mouse models of P. gingivalis infection periodontitis and observed that periodontitis mice exhibited higher levels of cGAS and STING protein and secreted more inflammatory cytokines than control mice." (PMID 37405166, 2023). "In summary, we have demonstrated that P. gingivalis infection contributes to the progression of the inflammatory response via the cGAS-STING signaling pathway in HGFs and a mouse model of periodontitis." (PMID 37405166, 2023). "In the present study, we first found that P. gingivalis infection triggers type I IFN gene and related cytokine expression and leads to activation of the cGAS-STING pathway both in vitro and in a periodontitis mouse model." (PMID 37405166, 2023). "It has been reported that gingival fibroblasts express cGAS and STING and produce various inflammatory cytokines, including IL-6, IL-8, and CCL2, in periodontitis." (PMID 37405166, 2023). "The cGAS-STING pathway, which is frequently found to be stimulated in periodontitis, may not only induce type I interferon responses but also promote M1 polarization by sensing cytosolic DNA." (PMID 38181706, 2024). "Moreover, the mRNA levels of cGAS and STING in periodontitis mice were 2-and 3-fold higher than those in the control group, respectively." (PMID 37405166, 2023). "However, it remains unknown whether and how P. gingivalis is involved in regulating the cGAS-STING signaling pathways in gingival tissues and its role in periodontitis pathogenesis." (PMID 37405166, 2023).